NRAS (NRAS proto-oncogene, GTPase)
Diseases named in the same sentence as NRAS in open-access papers (continued):
Sharing a sentence is not in itself a finding about the gene and the disease.
melanoma (continued). "The efficacy and safety results from an earlier data cut-off of February 29, 2012 (smaller subgroups of patients with NRAS- or BRAF-mutated melanoma) have been previously reported." (PMID 30956763, 2019). "AXL inhibition is shown to be pivotal in overcoming intrinsic or acquired resistance to BRAF/MEK inhibitors by melanoma harboring NRAS and BRAF mutations." (PMID 30651547, 2019). "The mutations of KRAS and BRAF oncogenes are involved in colorectal cancer and melanoma, while the NRAS mutations are associated with melanoma." (PMID 30935124, 2019). "While immune-based therapies are not genotype-specific, compared with their efficacy in other melanomas, they seem to be at least as effective, possibly more so, in the subset with NRAS mutations." (PMID 30999681, 2019). "Overall, the tumor genetic landscape for patients with BRAF- and NRAS-mutated melanoma was concordant with that reported in TCGA melanoma cases." (PMID 30956763, 2019). "KRAS mutations are exceedingly common in pancreatic adenocarcinomas and colorectal cancers, while NRAS mutations are more common in melanomas, thyroid cancers, and leukemias." (PMID 31681559, 2019). "Another cohort of mutations driving the development of melanoma is found in the neuroblastoma RAS viral (v-ras) oncogene homolog (NRAS), which codes for a small guanine triphosphate (GTP)-binding protein." (PMID 30999681, 2019). "Multiregional analyses to include the precursor lesions have shown that BRAF and NRAS mutations are early drivers for melanoma tumorigenesis." (PMID 31277584, 2019). "BRAF and NRAS mutations, while being well-known risk factors and drivers of cancer onset, have limited prognostic significance for overall survival of melanoma patients." (PMID 31316083, 2019). "Recurring hotspot mutations in the V600 codon of BRAF or Q61 codon of NRAS are the most prevalent and occur in approximately 35–50% and 10–25% of melanomas, respectively." (PMID 30312528, 2019). "Regarding the other types of melanoma, NRAS mutations have been found in about 20% of cutaneous melanomas, 5–13% of mucosal melanomas and 10% of acral melanomas." (PMID 31683701, 2019). "The 38 target genes have been shown for miR-146a-5p of which NRAS gene is known asone of the most frequent mutated in melanoma." (PMID 30611259, 2019). "RAS oncogenes with activating mutations have been observed in a third of all human cancers; 15–20% of melanomas carry NRAS mutations, most frequently at hotspots in exon 2 (codon 61) (NRAS Q61L/R)." (PMID 30999681, 2019). "Of note, it was recently demonstrated that CIMP is prevalent in melanoma patients with specific genetic alterations, including NRAS, ARID2, and IDH1 mutations." (PMID 31861757, 2019). "Surprisingly however, the comparison also showed a noticeable difference between cutaneous and mucosal melanomas regarding the location of NRAS mutations." (PMID 31398831, 2019). "The secondary acquisition of an NRAS* mutation in a BRAF* melanoma cell has also been described in the context of therapeutic resistance." (PMID 30651601, 2019). "There were 9 patients who developed melanoma in the first 5 years of life, and 7 patients revealed a Q61K mutation in the NRAS gene." (PMID 30782194, 2019). "Mutations of NRAS appear in codons 12, 13 and 61 and arise in 15%–20% of all melanomas and the mutant GTPase NRas (N-Ras) has been associated with aggressive clinical behavior and poor prognosis." (PMID 30935124, 2019). "CDK 4/6 inhibitors are currently being evaluated in combinations with BRAF and MEK inhibitors against BRAF- and NRAS-mutated melanomas." (PMID 31573152, 2019). "A total of 18 unique NRAS mutations were detected in 110 NRAS-mutated melanomas, including 2 tumors with 2 NRAS mutations." (PMID 31277584, 2019). "Mutations in HRAS can be found in dermatological malignancies and head and neck cancers, while NRAS mutations are common in melanomas and in some hematopoietic malignancies." (PMID 31681616, 2019).
melanoma (continued). "This is supported by the observation of a significantly higher incidence of coexisting KRAS/NRAS/HRAS mutations in melanomas with class-3 mutations." (PMID 31277584, 2019). "Although this is an uncommon NRAS variant, it has been reported in a small number of tumors, including melanoma, and potently induces MAPK signaling." (PMID 31795494, 2019). "NRAS mutation status has been shown to be a useful independent predictor of shorter survival rates following diagnosis with Stage IV melanoma." (PMID 30999681, 2019). "NRAS mutation frequencies were relatively comparable between melanoma and naevi (both approximately 20%)." (PMID 30995742, 2019). "To better understand the molecular pathogenesis of mucosal melanoma we compiled NRAS mutations in 1387 mucosal melanoma from 36 publications and added the data from 67 mucosal melanomas from our own research center." (PMID 31398831, 2019). "Follow-up analysis evaluated how CDK11 loss alters cell cycle function in BRAF- and NRAS-mutant melanoma cells." (PMID 30987032, 2019). "We also employed DMBC22 cell line that was previously assigned to the NRAS subtype of melanoma as it harbored a homozygous NRASQ61R variant and a wild-type BRAF." (PMID 30989459, 2019). "CD8 T-cells suppress resistance development to MAPK inhibitors in BRAF and NRAS-mutant melanoma with high mutational burden and targeting IPRES can enhance the anti-tumor activity of combined BRAF inhibitor and anti-PD-1 antibody." (PMID 31416487, 2019). "The commonest oncogenic driver mutation is BRAFV600E, present in up to 50% of cases, followed by NRAS codon 61, mutated in about 20% of melanomas." (PMID 31257073, 2019). "In order to better evaluate the accuracy of the model, we checked the effect of BRAF and NRAS mutation or wild-type on the prognostic ability of melanoma in the same cohort." (PMID 31649871, 2019). "In contrast to pancreatic, lung, and colon cancers, melanomas contain NRAS mutations in 20–30% of cases NRAS is also commonly mutated in acute myeloid leukemias in 15% of cases." (PMID 31681559, 2019). "According to the histologic subtype, NRAS mutations are present in 31% of NMs, in 21% of superficial spreading melanomas (SSMs), in 8% of acral lentiginous melanomas (ALMs), and in 19% of Lentigo Malignas (LMs)." (PMID 30934534, 2019). "The data showed that NRAS mutations were present in 12% (179/1454) of mucosal melanoma, and 54% (96/179) were located on Q61, 31% (56/179) on G12, and 15% (27/179) on G13." (PMID 31398831, 2019). "Although some driver mutations in BRAF or NRAS genes have been identified in melanoma, the efficiencies of their inhibitors are still limited." (PMID 31231466, 2019). "A weak association between specific mutations or total number of mutations with either measure of efficacy was shown among patients with either BRAF- or NRAS-mutated melanoma (respectively)." (PMID 30956763, 2019). "This equivalence also contributes to the validation of these biomarker results, leading toward a better understanding of changes that occur within patients with BRAF- and NRAS-mutated melanoma and their predictive value." (PMID 30956763, 2019). "Among melanoma patients, the co-existence of hTERT promoter and BRAF/NRAS mutations were related to 2-fold reduced disease-free and 5-fold reduced melanoma-specific survival." (PMID 31186051, 2019). "This study thus defined SPRY4 as a potential mediator of synthetic suppression, which is likely to contribute to the observed exclusivity between BRAF(V600E) and NRAS(Q61R) mutations in melanoma." (PMID 30651601, 2019).
melanoma (continued). "Comparison of patients in the BRAF- and NRAS-mutated arms with TCGA melanoma cases showed overall concordance of the tumor genetic landscape with regard to the percentage of patients experiencing alterations in the most frequently mutated genes." (PMID 30956763, 2019). "No patients had a complete response, and 6 of 30 patients (20%) with NRAS-mutated melanoma (3 confirmed) and 8 of 41 patients (20%) with BRAF-mutated melanoma (2 confirmed) had a partial response." (PMID 30956763, 2019). "In NRAS-mutated advanced melanoma, a progression-free survival benefit was observed in patients treated with binimetinib (a MEK inhibitor) compared with dacarbazine." (PMID 31277584, 2019). "In contrast, NRAS mutations are mainly found in melanoma, hematopoietic, and lymphoid tissue malignancies, and to a lesser extend thyroid tumors." (PMID 31398831, 2019). "This open-label phase II study assessed the use of binimetinib in patients with BRAFV600- or NRAS-mutated advanced melanoma." (PMID 30956763, 2019). "Sixteen out of 18 NRAS Q61 mutated melanomas and one out of 2 NRAS G12 mutant melanomas showed a positive expression for CK2α, with higher expression levels in the NRAS Q61 mutant samples." (PMID 31681616, 2019). "Our data presented herein demonstrate that CDK11 is highly expressed in both BRAF- and NRAS-mutated melanoma cell lines." (PMID 30987032, 2019). "NRAS-mutated melanomas were shown to respond to MEK1/2 inhibition in a small percentage of cases, which has, however, not led to an approval for treatment of melanoma patients carrying NRAS mutations." (PMID 30987166, 2019). "NRAS is second in the percentage of recurrently mutated genes in melanoma and accounts for close to 30% of mutated melanomas in a mutually exclusive way with BRAF." (PMID 30987166, 2019). "It is well known that in melanoma, pancreatic cancer, lung cancer, bladder cancer and acute myeloid leukemia, NRAS mutations are commonly found." (PMID 31412876, 2019). "The second most important mutated oncogene is the neuroblastoma RAS viral oncogene homolog (NRAS) which is mutated in close to 30% of all melanomas." (PMID 30987166, 2019). "The second most common mutation in melanoma affects the NRAS gene in codon 61, producing such mutations as Q61R or Q61K." (PMID 31635389, 2019). "Mutations in NRAS only occur in 10–20% of mucosal melanomas, while mutations in GNAQ and GNA11 that are commonly detected in uveal melanoma, occur in approximately 9.5% of mucosal melanomas." (PMID 30847022, 2019). "NRAS mutations that activate the MAPK/ERK pathway occur in 15–20% of melanomas and result in the reduction of intrinsic GTPase activity and the constitutive activation of NRAS." (PMID 30953523, 2019). "The data reported in this study suggest that in visceral metastases of malignant melanoma BRAF- or NRAS-mutant allele fractions are rather heterogeneous and are quite difficult to predict based on data from the primary tumor." (PMID 31391014, 2019). "Overall, there are no currently available small molecule inhibitors that have reasonable activity in NRAS-mutated melanomas." (PMID 30987166, 2019). "This binding triggers the sustained activation of the MAPK and the PI3K/AKT pathways, which are frequently upregulated in melanomas through NRAS or BRAF mutation, or PTEN loss, respectively." (PMID 31013837, 2019). "In treatment monitoring, single gene analysis require identification of an early event in the tumour and for melanoma BRAF/NRAS hotspot mutations are good candidates." (PMID 31767937, 2019). "Treatment of BRAFV600E melanomas invokes resistance in BRAFV600E melanoma cells, with mechanisms of resistance including the development of upstream mutations in NRAS or KRAS." (PMID 29481571, 2018). "In melanoma, point mutations N375S, T1010I and R988C, which were associated with NRAS and BRAF mutations, were detected." (PMID 29455657, 2018).
melanoma (continued). "On the other hand, the loss of miR-204 was enriched in melanomas with NRAS sole mutation (Fisher exact test, P = 0.001, Log Odds = 1.67), and less frequent than expected in those harbouring CDKN2A mutations (Fisher exact test, P = 0.001, Log Odds - 1.09)." (PMID 29523154, 2018). "Better objective response rates were associated with metachronous metastases (P = 0.04), PD-L1 tumour- and/or immune-cell status (P = 0.01), CD163+ histiocytes at advancing edges (P = 0.009) of primary melanomas and NRAS mutation (P = 0.019)." (PMID 29973670, 2018). "The findings of this study suggest that melanoma patients with BRAF or NRAS mutant tumours have an increased risk compared to patients with BRAF/NRAS wild-type tumours of developing disease recurrence following a tumour-negative SLNB." (PMID 29755118, 2018). "KRAS/NRAS mutations are therapeutically relevant for melanomas, colorectal cancer, and thyroid cancer (OncoKB level 3)." (PMID 30442178, 2018). "As for the BRAFV600E, also the importance of NRAS mutations in melanoma development has been studied in GEMMs." (PMID 29534457, 2018). "Since NRasQ61K is the most relevant oncogene to human melanoma, with 30% of melanomas having contributing mutations in NRas, it was prioritised for the purpose of this study." (PMID 29666124, 2018). "In melanoma, activating NRAS mutations (mainly at codon 61 and more rarely on codon 12–13) are found in approximately 20% of tumors." (PMID 29946532, 2018). "In particular, melanomas with NRAS mutations are highly resistant to most therapies and have poor prognosis." (PMID 29695835, 2018). "Oncogenic mutations in NRAS are present in over 25% of melanomas and patients whose tumors harbor NRAS mutations have limited therapeutic options and poor prognosis." (PMID 29695835, 2018). "Of note, TERT levels were downregulated following NRAS depletion in both NRAS-mutant melanoma cells harboring TERT promoter mutations and to a lesser degree in melanoma cells with wild-type TERT promoter." (PMID 29695835, 2018). "Treatment with 6-thio-dG impaired the viability of NRAS-mutant melanoma cells, including cells driven by the secondary mutations in NRAS derived from melanoma patients with acquired resistance to BRAF and MEK inhibitors." (PMID 29695835, 2018). "Clinically, BRAF or NRAS-mutant melanoma patients whose tumors have TERT promoter mutations have poor overall survival compared to patients with tumors with a non-mutated TERT promoter." (PMID 29695835, 2018). "Again, xenograft models were then used to test the efficacy of targeted therapies in NRAS mutated melanomas." (PMID 29534457, 2018). "While activating mutations in the BRAF gene were discovered in around 50% of melanoma patients, mutations in NRAS account for 21–28% of melanomas." (PMID 29534457, 2018). "Illustrating this, BRAF V600E and NRAS Q61R appeared to be selected more strongly than KRAS G12D in melanoma and thyroid cancer, but more weakly than this mutation in pancreatic cancer." (PMID 29748584, 2018). "This novel combination was recently found to be robustly effective in NRAS mutated melanoma tumor models, whereas synergistic antitumor activity was observed both in vitro and in vivo." (PMID 29402316, 2018). "For instance, approximately 20% of melanoma patients have tumors carrying mutations in NRAS, and of these approximately 80% have amino acid substitutions at position 61, including Q61R (38%), Q61K (24%), and Q61L (15%)." (PMID 29854275, 2018). "In preclinical models, ribociclib also showed some activity in melanomas with activating mutations of BRAF or NRAS." (PMID 30631751, 2018). "NRAS-mutated melanoma cell lines (SB2 and SK-Mel-2) migrate efficiently toward HGF but this process is completely inhibited by PHA-665752, and treatment with 50–100 nM PHA-665752 inhibited phosphorylation of Akt." (PMID 29455657, 2018).
melanoma (continued). "This better response of NRAS-mutated melanoma to immune therapy is due to a higher level of immunosuppression in the tumor microenvironment compared to BRAF-mutant melanoma." (PMID 30360441, 2018). "The effects of similar combination strategy have also been reported in two other studies: MEK1/2i with docetaxel (a microtubule poison) reduced mammary tumor growth in vivo, and a MEK1/2‐PLK1 inhibition caused regression of NRAS mutant melanoma xenografts." (PMID 30108112, 2018). "LY3009120 inhibited the proliferation of melanoma cells with either BRAF or NRAS and colorectal cancer cells with BRAF and KRAS mutations by inducing G0/G1 cell cycle arrest." (PMID 29455659, 2018). "Among the 9 primary melanoma samples which presented mutations at codon 61 of NRAS gene, 7 were successfully amplified for TERT: 4 (57%) showed mutations in TERT promoter and 6 (86%) presented the –245T>C polymorphism." (PMID 29464027, 2018). "As there exist no specific NRAS/Ras inhibitors, different strategies for treatment of NRAS-mutated melanomas were administered for therapy." (PMID 30360441, 2018). "In a non-randomized, open-label phase II study of advanced melanoma patients harboring NRAS or VAL600 BRAF mutations, binimetinib showed a partial response, providing the first target therapy to treat patients with NRAS-mutated melanomas." (PMID 29455659, 2018). "Relative MEK and ERK phosphorylations were diminished at increasing concentrations of 17-AAG in BRAFV600E and NRAS mutated human melanoma cell lines." (PMID 29481571, 2018). "Immune therapies of NRAS-mutated melanomas are now the first-line treatment for NRAS and WT melanoma." (PMID 30360441, 2018). "Although the oncogenic expression of mutated BRaf or NRas elicits anomalous melanocyte proliferation, they are insufficient to induce melanoma development." (PMID 29464040, 2018). "The BRAF and NRAS mutations are mutually exclusive in melanomas, suggesting that mutation in single gene locus is enough to over-activate the downstream Extracellular signal-regulated kinase (ERK) pathway." (PMID 30544544, 2018). "In melanoma patients, the presence of NRAS mutation was identified as a predictor of poorer outcomes and turned out to be associated with worse median overall survival (OS)." (PMID 29682098, 2018). "Next to the more common BRAF oncogene, mutations in the NRAS gene result in more aggressive melanomas." (PMID 30360441, 2018). "Melanoma patients with BRAF or NRAS mutant tumours had an increased risk compared to patients with BRAF/NRAS wild-type tumours of developing disease recurrence following a tumour-negative SLNB." (PMID 29755118, 2018). "Since RAS activates the MAPK signaling pathway, the idea to overcome the direct targeting of NRAS by hitting the RAS-MAPK downstream effectors was pre-clinically tested in xenograft models of NRAS mutated melanoma." (PMID 29534457, 2018). "NRAS (22%) and HRAS (9%) isoforms are less frequently mutated with melanomas accounting for half of NRAS mutant patients, while head and neck cancer and bladder cancer together account for half of HRAS mutant patients." (PMID 30287508, 2018). "Although, a tumor situated in the lung is more likely to be lung cancer, the lung is a frequent site of metastatic spread especially in patients with NRAS-mutated melanoma and primary melanoma of the lung is recognized in the literature as well." (PMID 30205833, 2018). "Somatic mutations in KRAS are common in gastric cancer tumors, NRAS is frequently mutated in melanoma, and HRAS to some extent in breast cancer." (PMID 30597917, 2018). "Specific KRAS/NRAS mutations are correlated with differences in protein profiles for melanomas and thyroid cancer and also for testicular germ cell tumors, endometrial carcinoma, and lung adenocarcinoma (in conformity with OncoKB level 4 data)." (PMID 30442178, 2018).